STK33 (serine/threonine kinase 33)
Diseases named in the same sentence as STK33 in open-access papers (continued):
Sharing a sentence is not in itself a finding about the gene and the disease.
cancer (20 papers, 2013 to 2025). A tumor composed of atypical neoplastic, often pleomorphic cells that invade other tissues. "Given its established association with tumorigenesis, developing potent STK33 inhibitors represents a promising therapeutic strategy for targeted treatment of cancer." (PMID 40908551, 2025). "STK33 has been reported to be associated with cell proliferation as well as EMT in various cancer types." (PMID 35130915, 2022). "Even though the STK33 inhibitory function of Z29077885 associated with the anticancer effect needs to be further investigated, a new anticancer drug repurposed by AI can be a promising therapeutic agent against cancers." (PMID 38087254, 2023). "Decreased HIF-1α abundance in cancer cells with STK33 deletion and exposed to hypoxia was associated with significantly impaired transcriptional activation of the HIF-Responsive Element (HRE), a HIF-1α docking site present in promoters that contain the RCGTG sequence." (PMID 29100402, 2017). "Cancer cells transduced with an expression vector encoding STK33 were xenografted on chicken CAM." (PMID 29100402, 2017). "One could argue that the loss of stk33 may be beneficial, since it has been identified as an essential component in several types of cancer." (PMID 26199010, 2015). "However, overexpression of STK33 partially reverted the cytotoxicity of PU-H71 as indicated by restored tumor formation and was associated with higher number of Ki67 positive cancer cells as compared with tumors transduced with empty vector." (PMID 29100402, 2017). "On the other hand, STK33 has been identified as a survival factor in KRAS-mutant cancers, stabilized by the HSP90/CDC37 complex." (PMID 41009685, 2025). "This study not only establishes Bufalin as a putative STK33 degrader to suppress TNBC but also identifies STK33 as a pro‐cancer factor in TNBC, presenting a potential therapeutic target for TNBC." (PMID 40908551, 2025). "We demonstrate that Z29077885 can inhibit STK33 enzymatic function in vitro and decrease cell viability regardless of the KRAS mutation status and STK33 expression level in cancer cells." (PMID 38087254, 2023). "Serine/threonine kinase 33 (STK33) is a member of the calcium/calmodulin-dependent kinase family and is implicated in various cancers." (PMID 38087254, 2023). "STK33 as a potential therapeutic target in cancer is controversial since several known STK33 inhibitors neither inhibit cancer cell proliferation nor induce cancer cell death." (PMID 38087254, 2023). "In this study, we identified a new anti-cancer drug targeting STK33 that induces apoptosis and cell cycle arrest at s phase by AI." (PMID 38087254, 2023). "Various inhibitors of STK33 have been developed, and kinase-dependent and -independent roles of STK33 in malignant tumors have been demonstrated." (PMID 38087254, 2023). "Next, we demonstrated that Z29077885 inhibits Serine/threonine kinase 33 (STK33) enzymatic function in vitro and showed the anticancer efficacy in various cancer cells." (PMID 38087254, 2023). "Once the STK33 kinase inhibitory function of the compound was confirmed, we next tested its anticancer efficacy in various cancer cell lines with various STK33 expressions for a comprehensive understanding of the drug." (PMID 38087254, 2023). "In this study, we used an AI-driven screening strategy to find a novel anticancer medication targeting STK33 that triggers cancer cell apoptosis and cell cycle arrest at the s phase." (PMID 38087254, 2023). "STK33 (serine/threonine kinase 33) is a serine/threonine kinase and plays an important role in cancer cell proliferation." (PMID 35280808, 2022). "Broadening the search to genes previously associated with other cancer types in Cancercensus, we identified three other genes overlapping with CpG sites identified as candidate CpGDMs (HMGA2, GNA13, and STK33)." (PMID 33145876, 2021).
cancer (continued). "Four of the 11 affected genes were associated with different cancer types: MUC6 and ZNF717 (prostate), SPEN (breast), and STK33 (pancreas)." (PMID 33968136, 2021). "Lately, the HSP90 client serine/threonine kinase STK33 emerged to be required by cancer cells for their viability and proliferation." (PMID 29100402, 2017). "Our previous study showed that pharmacologic inhibition of HSP90 resulted in destabilization and subsequent proteasome-mediated degradation of STK33 in various cancer cell lines." (PMID 29100402, 2017). "In order to investigate a potential direct role of STK33 in tumor cell proliferation, several cancer cell lines were stably transduced with lentiviral vectors encoding two STK33-specific shRNAs or a non-coding shRNA." (PMID 29100402, 2017). "In our experimental model, cancer cells overexpressing STK33 and exposed to HSP90 inhibitor displayed a partial rescue of HIF-1α transcriptional activity and secreted VEGF-A." (PMID 29100402, 2017). "In other words, tumors highly expressing STK33 are prone to a rapid development once they reach a certain level of hypoxia, a fact that would render the expression of STK33 as tumor marker for hypoxic cancers." (PMID 29100402, 2017). "We previously identified STK33 as a client of HSP90, a chaperone known to stabilize and activate multiple proteins, several of which are mutated or highly expressed in human cancers." (PMID 29100402, 2017). "Further study should be focused on the identification of a direct substrate for STK33 so as to determine the precise role of STK33 gene in the initiation and progression of cancer cells." (PMID 25603720, 2015). "STK33, a relatively understudied protein, has been linked to KRAS mutation-driven cancers and explored as a potential antineoplastic drug target." (PMID 23967198, 2013). "Rs4929949 is located within intron 1 of the gene encoding STK33, a pharmacologically targeted serine/threonine kinase reported to be involved in KRAS-mediated cancers." (PMID 23967198, 2013). "A growing body of evidence suggests that STK33 is a promising therapeutic target for cancer." (PMID 40908551, 2025). "STK33 is involved in cancer initiation, progression, and resistance to therapy." (PMID 38087254, 2023). "All these data indicate that the nonkinase activities of STK33 can be responsible for its observed essentiality for the cancer cells harboring KRAS mutations." (PMID 34955846, 2021). "It is shown that knockdown of STK33 leads to a decrease in viability of KRAS mutant cancer cells." (PMID 34955846, 2021). "Today, little is known about the role of STK33 in the biology of cancer." (PMID 34955846, 2021). "Interestingly, another kinase named STK33 was also previously found to be critical for KRas-dependent cancer cells." (PMID 34955846, 2021). "In contrast, if STK33 expression was suppressed by knocking down STK33 in cancer cell lines which expresses high levels of STK33, we want to know whether tumorigenic properties can be reduced." (PMID 30760631, 2019). "The human serine/threonine kinase 33 (STK33) enzyme belongs to calcium/calmodulin-dependent kinase family and is located on chromosome 11p15.3, which is a gene-rich region associated with several diseases, including cancer." (PMID 30760631, 2019). "STK33 is a novel serine/threonine kinase that has been the focus of cancer studies in recent years." (PMID 30760631, 2019). "STK33 knock-down resulted in impaired cancer cell proliferation and increased apoptosis." (PMID 29100402, 2017). "Furthermore, degradation of STK33 by HSP90 inhibition preceded apoptosis while ectopic expression of the kinase was able to rescue cancer cell viability after HSP90 inhibitor treatment." (PMID 29100402, 2017). "Finally, our study favors the use of HSP90 inhibitor PU-H71 (currently undergoing clinical evaluation) to target cancer growth and vascularization particularly in hypoxic tumors with high expression of STK33." (PMID 29100402, 2017).
cancer (continued). "Furthermore, to our surprise, we found that at least in certain cancer cell lines / tumor entities, elevated STK33 expression can further boost the hypoxia-triggered HIF-1α activation and subsequent vascularization." (PMID 29100402, 2017). "Several studies during the last decade revealed the emerging role of STK33 in cancer." (PMID 29100402, 2017). "Altogether, these data suggest that STK33 is expressed in tumor tissues and may play an important role in cancer progression." (PMID 29100402, 2017). "Having demonstrated that STK33 is required for cancer cell growth in vitro, we further investigated the effect of STK33 abrogation in tumor formation in vivo using the chicken chorionallantoic membrane (CAM) assay, an established model of in vivo tumor formation." (PMID 29100402, 2017). "Furthermore, stk33 has attracted attention since it has been identified as an essential component for the survival of KRAS-dependent cancer cells by high-throughput RNA interference (RNAi) screens." (PMID 26199010, 2015). "Nevertheless, analyzing if neognaths display any form of immunity to these types of cancer could represent an interesting approach, since they constitute natural knockouts for stk33." (PMID 26199010, 2015). "As the aberrant activation of Wnt/β‐catenin signaling is indispensable for maintaining cancer's malignant phenotype, our finding provides evidence that STK33 may be a key molecule in Wnt/β‐catenin signaling, and targeting STK33 is critical for the treatment of TNBC." (PMID 40908551, 2025). "Thus, MACC1-AS1 could enhance the stability of STK33 by inhibiting its ubiquitination, leading to the increased accumulation of STK33 in cancer cells." (PMID 38413579, 2024). "Therefore, we confirmed Z29077885 as a new anticancer agent targeting STK33 in vitro and in vivo, discovered using the AI deep learning method; this might provide clinical benefits during cancer treatment." (PMID 38087254, 2023). "However, it remained unclear whether chaperone-stabilized STK33 participates in tumor progression by affecting cancer cell viability only or whether it is also involved in an HSP90-maintained angiogenic program." (PMID 29100402, 2017). "Consequently, we sought to find out whether STK33 might regulate this oxygen sensor protein in hypoxic cancer cells." (PMID 29100402, 2017). "Although the therapeutic potential of inhibiting STK33 in patients with KRAS-mutant cancer is controversial, STK33 remains an attractive therapeutic target in several other cancers." (PMID 38087254, 2023). "The results showed that STK33 were highly expressed in 17 CRC cell lines, moderately expressed in three cancer cell lines and only low expressed in two cancer cell lines, respectively." (PMID 30760631, 2019). "On the one hand, STK33 expression was detected by immunohistochemistry tissue array analyses in normal colorectal tissue and matching CRC tissue samples from 59 cancer patients (IMGENEX)." (PMID 30760631, 2019). "Recently we identified STK33 as a client of HSP90 and demonstrated that is required for cancer cell viability supported by the chaperone." (PMID 29100402, 2017). "Mechanistic studies demonstrated that HSP90-stabilized STK33 interacts with and regulates hypoxia-driven accumulation and activation of HIF-1α as well as secretion of VEGF-A in hypoxic cancer cells." (PMID 29100402, 2017). "This work reveals a new role of STK33 during tumor progression, namely the participation to the regulation of HIF-1α and its target gene VEGF-A in hypoxic cancer cells." (PMID 29100402, 2017). "Notably, the STK33 expression was found to be correlated with poor prognosis in TNBC, which promotes cancer cell proliferation and migration via the CCAR1/β‐catenin pathway." (PMID 40908551, 2025). "Furthermore, ectopic STK33 also partially rescued VEGF promoter activity as well as VEGF secretion in hypoxic cancer cells subjected to HSP90 inhibition." (PMID 29100402, 2017).
cancer (continued). "In addition, our study reveals a putative cooperation between STK33 and other HSP90 client protein kinases involved in molecular and cellular events through which cancer cells ensure their survival by securing the oxygen and nutrient supply." (PMID 29100402, 2017). "However, a new study demonstrates that STK33 activity is nonessential in KRAS-dependent cancer cells." (PMID 25603720, 2015). "Although STK33 has not been directly associated with body mass regulation previously, it is of particular interest because of its potential involvement in GTPase KRas (KRAS) driven cancers and the fact that STK33 has also been targeted pharmacologically." (PMID 23967198, 2013). "However, STK33-targeting cancer therapeutics have not been approved for patient-use yet." (PMID 38087254, 2023). "However, the role of stk33 in KRAS-dependent cancer cells remains disputed because other research groups were not able to find a correlation between the knockdown or inhibition of stk33 and KRAS-dependent cancer cell survival, neither using RNAi nor small molecule inhibitors." (PMID 26199010, 2015). "However, the role of stk33 in cancer remains controversial and we do not have any indication for a beneficial effect due to the lack of stk33, making this a rather unlikely hypothesis." (PMID 26199010, 2015). "Additionally, other STK33 inhibitors, including ML-281, failed to rescue the survival rate of KRAS-dependent cancer cells." (PMID 38087254, 2023).
tumor (16 papers, 2015 to 2025). "In summary, our research findings align with previous studies and aim to investigate and validate the underlying mechanisms of STK33 in tumor drug resistance." (PMID 38413579, 2024). "It has also been demonstrated that STK33 involved in the ‘synthetic lethality’ process in a variety of tumor cells, which occurs when deficiency in the expression of multiple genes results in cell death and depends on the Ras oncogene." (PMID 30760631, 2019). "This is also supported by in vitro study showing that KRAS mutant tumours are more susceptible to HSPC1 inhibitions via degradation of STK33." (PMID 28255900, 2017). "Most importantly, enhanced proliferation in tumors ectopically expressing STK33 was paralleled by augmented levels of desmin, an observation that suggests a causal relationship between STK33 expression and tumor angiogenesis downstream of HSP90." (PMID 29100402, 2017). "Elevated endogenous STK33 level in hypopharyngeal squamous cell carcinoma (HSCC) was associated with clinico-pathological hallmarks of tumor aggressiveness." (PMID 29100402, 2017). "Impaired proliferation and augmented apoptosis associated with genetic abrogation of STK33 were paralleled by decreased vascularization in tumor xenografts." (PMID 29100402, 2017). "Therefore, many questions related to STK33 in tumor cells remains controversial and the mechanisms underlying the function of STK33 in tumor biology are complex." (PMID 30760631, 2019). "The pro and con evidence indicates that the role of STK33 in tumor cells remains controversial and, from another angle, reflects that the mechanism underlying the action of STK33 to alter the nature of tumor may be much more complex." (PMID 25603720, 2015). "Moreover, statistical analyses showed that there existed significant associations between STK33 expression in HSCC with tumor size, clinical stage, and lymph node metastasis." (PMID 25603720, 2015). "Our findings provide a complementary tool for developing STK33 degrader with potential anti‐tumor properties." (PMID 40908551, 2025). "We also examined the effect of Bufalin on the expression of STK33 in tumor tissues through immunohistochemistry and western blot assay." (PMID 40908551, 2025). "Fifty‐one candidate proteins were identified, and we selected three top‐ranked, tumor‐related candidates (STK33, CLCN3, and RhoA) from the top 15 ranked proteins for further validation using SPR assays." (PMID 40908551, 2025). "On the other hand, it is demonstrated that inhibition of HSP90 (by shRNA or small molecules) led to a decrease in protein content of STK33 and reduction of viability in vitro and tumor growth rate in vivo for KRAS mutant CRC cell lines." (PMID 34955846, 2021). "The tumors in NCM460-STK33-injected mice first appeared at 17 days, and the final average tumor weights and tumor growth curves showed that STK33 overexpression promotes NCM460 cells tumorigenic in vivo." (PMID 30760631, 2019). "For instance, the HPA reports that STK33 is localized mainly in the nucleus of tumor cell lines cultured in vitro, but, in tissue sections (either healthy or tumor), STK33 is mainly cytoplasmic." (PMID 30149579, 2018). "In line with this, ectopic STK33 not only promoted tumor growth after pharmacologic inhibition of HSP90 using structurally divergent small molecules currently in clinical development, but also restored blood vessel formation in vivo." (PMID 29100402, 2017). "In this work we identified STK33 as an essential HSP90 client that participates in a complex tumor angiogenic program coordinated by the chaperone." (PMID 29100402, 2017).